NFIB (nuclear factor I B)
Diseases named in the same sentence as NFIB in open-access papers (continued):
Sharing a sentence is not in itself a finding about the gene and the disease.
tumor (continued). "To further investigate the regulatory network associated with CHD6, we predicted its upstream TFs based on scATAC-seq data of tumor cells and revealed that NFIB was one of the upstream regulators." (PMID 34824203, 2021). "As a second approach we used patient-derived ACC cells that represents a second type of MYB-dependent neoplasm that is associated with the expression of oncogenic MYB-NFIB fusion proteins due to MYB and NFIB gene fusions." (PMID 35008207, 2021). "MiR-302a has been found to act as a tumor suppressor by targeting NFIB (Nuclear factor 1 B-type) and downregulating the NFIB/ITGA6 axis, which is responsible for cell migration and invasion in the metastatic process." (PMID 33801049, 2021). "In conclusion, we confirmed that NFIB can promote the proliferation and metastasis of tumor cells by transcriptionally regulating the expression of PINK1 in KIRC." (PMID 33981484, 2021). "In view of these results, we consider it necessary to further investigate the role of NFIB in KIRC tumor growth and metastasis." (PMID 33981484, 2021). "Studies in SCLC have also revealed NFIB as a downstream target of c-Myc, which directly regulates its expression and contributes to tumor aggressiveness and rapid metastases." (PMID 34922631, 2021). "We further used colony formation experiments to demonstrate that the overexpression of NFIB promoted the number of tumor cell colonies formed in the LoMet-ccRCC and 786-0 cell lines." (PMID 33981484, 2021). "Immunohistochemistry results of tumour and normal tissues were scored as described in the Materials and Methods, and results indicated that expression of NFIB in CRC tissue was higher than in normal tissue." (PMID 33061846, 2020). "Mechanistically, hsa_circ_0026416 acts as a ceRNA for miR-346 to upregulate NFIB and promote tumour progression." (PMID 33061846, 2020). "Our findings show that miR-346 functions as a tumor suppressor marker by negatively regulating NFIB expression." (PMID 31807116, 2019). "NFIB, a previously reported tumor promotor in many kinds of cancers, shared sequence complementarity in its 3′-UTR with the miR-346 seed sequence, which was confirmed by luciferase report assays." (PMID 31807116, 2019). "Heterogeneous BRN2 and NFIB staining throughout the tumour was detected across all three tumour lines with co-localisation evident in most cells." (PMID 28119061, 2017). "The exception to this inter-tumor genomic diversity is a translocation targeting c-Myb and NFIB, creating a fusion gene in > 40% of ACC tumors." (PMID 28415633, 2017). "The tumourigenic assays performed here show that NFIB overexpression impaired the ability of these cells to form tumours in nude mice at the site of injection." (PMID 28119061, 2017). "The diverse cellular functions of NFIB are further corroborated by studies reporting its oncogenic or tumor suppressor roles in different tumor types." (PMID 27533466, 2016). "Ectopic expression of NFIB inhibited the intracranial xenograft tumour growth of both classical and mesenchymal GBM but did not inhibit the growth of proneural or neural GBM." (PMID 27083054, 2016). "Compared to grade II/III tumours, we found that NFIB expression was significantly lower in GBM samples." (PMID 27083054, 2016). "Here, we investigated the function of NFIB in human GBM and the potential clinical relevance of NFIB as a tumour suppressor in GBM biology." (PMID 27083054, 2016). "The expression of astrocyte-associated markers is up-regulated in three mesenchymal and two classical GBM cell lines in response to NFIB expression, which also occurs in primary tumours of these subtypes." (PMID 27083054, 2016). "We next sought to identify possible mechanisms by which NFIB exerted its GBM subtype-specific tumour-suppressive effect." (PMID 27083054, 2016). "Although the molecular mechanisms by which NFIB mediates its anti-tumour effects in GBM remain to be defined, our findings suggest a role for p-STAT3." (PMID 27083054, 2016).
tumor (continued). "Furthermore, following castration surgery in nude mice, subcutaneous implantation of C42B‐ABi cells with stable knockdown of BCL6, SMAD3 and NFIB significantly suppressed tumor proliferation compared to the control group." (PMID 40470696, 2025). "NFIB has been reported to promote tumor growth, metastasis, and recurrence in various cancers." (PMID 39273015, 2024). "The third one is loss&CN-LOH on 9p (hotspot #11) that may target several tumor suppressors, among them SMARCA2, NFIB and PTPRD." (PMID 38473323, 2024). "Overexpression of NFIB is correlated with advanced tumor stages and metastasis in small cell lung cancers therefore, we hypothesize that methylation of NFIB may also regulate the progression of SCLC." (PMID 36690626, 2023). "MiR-30d suppresses NSCLC tumor invasion and migration by targeting Nuclear factor I B (NFIB)." (PMID 37190222, 2023). "Additionally, in DLBCL, a circular RNA circ_0003645 acts as a miRNA sponge to miR-335-5p, hence abolishing miR-335-5p’s tumor suppressive effect in targeting NFIB." (PMID 36672402, 2023). "Interestingly, NFIB seems to have paradoxical roles in cancer, acting both as a tumor suppressor and as an oncogene in different tissues." (PMID 37738673, 2023). "Therefore, the role of NFIB in the tumor is complex, and its role in CRC needs to be further clarified." (PMID 37491379, 2023). "NFIB is a widely studied transcription factor that participates in tumor progression." (PMID 37491379, 2023). "Interestingly, 3 of the 5 urea cycle enzymes were also upregulated in the NFIB cKO liver, although to a lesser degree compared with that in tumor tissues." (PMID 35655758, 2022). "In the context of tumor, the role of NFIB is tissue-specific." (PMID 35655758, 2022). "NFIB was highly expressed in EC sub‐clusters and MSCs but weakly expressed in tumour cells." (PMID 36305631, 2022). "It seems that the effect of NFIB in tumor biology is stage-specific." (PMID 35655758, 2022). "PCNA staining was stronger in NFIB cKO tumor tissue, indicating higher proliferating activity." (PMID 35655758, 2022). "Elevated NFIB levels could simply increase general metastatic seeding ability or tumor growth, but it is also possible that NFIB upregulation provides an additional advantage for growth in those specific microenvironments." (PMID 33296145, 2021). "Nuclear factor IB (NFIB) was a newly found tumor suppressor gene in various cancers." (PMID 33991027, 2021). "NFIB is overexpressed in different tumor subtypes and it affects tumor progression and metastasis." (PMID 33375067, 2020). "Ninety-three unique analyses revealed the NFIB mRNA expression level varied with the type of tumor." (PMID 32219034, 2020). "Collectively, these results suggest that miR-346 inhibits tumor growth in vivo by targeting NFIB." (PMID 31807116, 2019). "This may suggest that other MYB fusion transcripts possibly involving NFIB or other 3′ gene partners are present in these tumours." (PMID 31301736, 2019). "However, although this NFIB-driven transcription program promotes tumor growth and metastasis, it confers cisplatin sensitivity to tumors that are otherwise refractory to chemotherapy." (PMID 31827074, 2019). "NFIB can also act both as an oncogene and a tumor suppressor gene depending on the tumor type." (PMID 31426421, 2019). "In these models NFIB expression was found to be necessary and sufficient to support metastatic spread, an observation further supported by a correlation between high NFIB expression and an advance metastatic tumour grade in neuro-endocrine tumours from human patients." (PMID 28119061, 2017). "Importantly, these studies reveal that NFIB has the ability to promote dynamic changes in the chromatin state of tumour cells to facilitate migration, invasion, and metastasis." (PMID 28119061, 2017). "Thus, our results suggest that MITF levels regulated by NFIB downstream of BRN2 are key in tumour formation and growth." (PMID 28119061, 2017).
tumor (continued). "These two cell lines have a phenotype closest to mesenchymal GBM and therefore provided initial evidence that NFIB could suppress tumour formation in this aggressive tumour subtype." (PMID 27083054, 2016). "Taken together, these observations underscore the possibility that as an inducer of astrocyte differentiation, NFIB could function as a tumour suppressor in astrocytic tumours." (PMID 27083054, 2016). "Thus both NFIA and NFIB appear to function in a genetic context-dependent manner as either tumour suppressors or oncogenes." (PMID 27083054, 2016). "We therefore analysed whether NFIB expression correlated with these subtypes using data from The Cancer Genome Atlas (TCGA) dataset of patient tumour tissue, classified as either proneural, neural, classical or mesenchymal GBM." (PMID 27083054, 2016). "Ectopic NFIB expression activated phospho-STAT3 signalling only in classical and mesenchymal GBM cells, suggesting a mechanism through which NFIB may exert its context-dependent tumour suppressor activity." (PMID 27083054, 2016). "Moreover, we noticed that the expression of NFIB was upregulated in tumor cells from AEP, further implying that NFIB might have crucial effects on the enhanced activity of the EMT pathway in malignant cells." (PMID 34824203, 2021). "Moreover, miR-212-3p-expressing tumors exhibited decreased staining for Ki-67, c-Myc, and NFIB and elevated staining for cleaved caspace-3, strengthening our hypothesis of the tumor-suppressive role of miR-212 in group 3 MB tumors." (PMID 34922631, 2021). "When exposed to chemotherapy, the sensitive NFIB-positive compartment may be effectively eliminated, reflecting the initially good response, but leaving behind a “minor” resistant primary tumor compartment." (PMID 31189116, 2019). "Interrogation of the gene expression data set obtained from the PM, SC and LM tumour populations, reveals that relative NFIB expression is increased in the highly metastatic tumours, both subcutaneous (SC) and lung metastases (LM), when compared with the poorly metastatic (PM) tumour group." (PMID 28119061, 2017). "Finally, as NFIB is expressed by GBM cells including GBM cancer stem/tumour-initiating cells, and is rarely homozygously deleted or mutated, it may have therapeutic benefit in GBM if its expression can be increased." (PMID 27083054, 2016). "The NFIB-mediated tumor suppressive pathway may play critical roles in normal skin cells and depletion of NFIB by high level expression of miR-365 in CSCC tumors may disrupted the dominant anti-carcinogenic pathway which contributes the progression of CSCC tumors." (PMID 24949940, 2014). "The transcription factor NFIB is a recognized oncogene in SCLC, promoting tumor progression by regulating metastasis and proliferation." (PMID 42001853, 2026). "In adenoid cystic carcinoma (ACC), tumor-promoting fusion proteins of MYB and MYBL1 with nuclear factor IB (NFIB) were identified." (PMID 38835346, 2024). "Single-cell RNA sequencing (scRNA-seq) showed a positive correlation (R = 0.097, P = 1.2e–05) between the expressions of NFIB and NAMPT in epithelium-derived tumor cells of CRC." (PMID 37491379, 2023).
tumor (continued). "To gain a molecular understanding of the NFIB/CARM1 pathway, we perform ATAC-seq and RNA-seq on the same tumor biopsies obtained for TKO, TKO;NfibR388K and TKO;Carm1KO mutant mice." (PMID 36690626, 2023). "Overexpression of NFIB in SUM159PT, a human TNBC cell line with low metastatic potential (Fig EV3C), similarly decreased tumour latency (Fig EV3D) and increased metastasis, both in the orthotopic (Fig EV3E and F) and the experimental metastasis assays." (PMID 33751828, 2021). "However, at present, there was no report about the relationship between NFIB mutation and tumor, whether the expression changes of NFIB are related to specific pathological subtypes." (PMID 33981484, 2021). "With the overexpression of NFIB, the proliferation and migration ability of KIRC tumor cells was significantly improved." (PMID 33981484, 2021). "Overexpression of NFIB in GBM cells induces cell differentiation and inhibits tumor growth via signal transducer and activator of transcription 3 (STAT3) signaling mechanisms." (PMID 34012965, 2021). "Taken together, these results suggested that PINK1 is a critical target of NFIB and that PINK1 exerts tumor-promoting roles in KIRC." (PMID 33981484, 2021). "In NSCLC, miR-30d represses tumor cell proliferation and motility by directly targeting CCNE2 and NFIB." (PMID 34112238, 2021). "Gene fusions involving MYB, MYBL1, and NFIB, which were found in nearly 90% of our SAdCC cases, are currently considered to be the primary oncogenetic event in SAdCC, and RAS mutations may confer progressive or invasive features on the tumor cells, resulting in a worse prognosis for SAdCC patients." (PMID 29682203, 2018). "EZH2 was expressed heterogeneously throughout each tumour, and showed distinct colocalisation with both BRN2 and NFIB." (PMID 28119061, 2017). "Our data provides strong evidence showing that these heterogeneous EZH2 expressing tumour populations are also BRN2 and NFIB positive and are likely mediated by BRN2 expression in an NFIB dependent manner." (PMID 28119061, 2017). "This analysis also revealed a significant inverse correlation between MITF and NFIB expression in metastatic tumour lines, with MITF levels decreasing as NFIB levels increase (P < 0.0068)." (PMID 28119061, 2017). "It is essential that we make inroads to understand the pathways through which NFIB and other SCLC driver genes control the steps between tumor initiation and metastatic progression." (PMID 27613844, 2016). "Importantly, we investigated the differential expression of BCL6, NFIB and SMAD3 in the tumor tissue samples and cell lines, with the findings indicating that these three genes are most highly expressed in CRPC and C42B‐ABi cells." (PMID 40470696, 2025). "Furthermore, this tumor type is characterized by recurrent molecular alterations, especially rearrangements involving the MYB, MYBL1, and NFIB genes." (PMID 37476370, 2023). "Consistently, the mRNA and pre-mRNA levels of NFIB were much higher in ICC tumor tissues than the paired nontumor tissues." (PMID 35039066, 2022). "In NFIB-silenced and miR-212-3p restored group 3 MB cells, we noted decreased expression of stemness markers, i.e. CD133, Sox2, Oct4, Nanog, and β-catenin, concurrent with reduced tumor cell self-renewal capacity as evidenced by sphere-forming assays." (PMID 34922631, 2021). "Hence, our data provide a new NFIB-mediated regulatory mechanism for the tumor progression of KIRC and suggest that NFIB can be applied as a new predictor and therapeutic target for KIRC." (PMID 33981484, 2021). "To investigate a potential LTF behavior of both TFs in NEPC, we performed SE analysis by H3K27ac profiling of ASCL1 and NEUROD1 NEPCs, and found that all models showed SE activation in common at a number of TFs (INSM1 and NFIB) regardless of the tumor subtype." (PMID 34599169, 2021).
tumor (continued). "One report stated that miR-1246 is oncogenic and that miR-1246 promotes cancer stemness by activating Wnt/β-actin signaling; the other report stated that miR-1246 is a tumor-suppresser and that miR-1246 inhibits cell proliferation of HCC by down-regulating nuclear factor I B (NFIB)." (PMID 30897788, 2019). "In this study, originally, NFIB expression is lower in both CSCC cells and patient tumor samples." (PMID 24949940, 2014). "Furthermore, TF footprint analysis has revealed tumor cell-specific binding TFs, including hepatocyte nuclear factor (HNF) family members, TEA domain transcription factor 3 (TEAD3), and nuclear factor I B (NFIB)." (PMID 41035074, 2025). "Furthermore, both patients with a diagnosis of lacrimal gland ACC in our study possessed this gene fusion; 69.2% of patients had NFIB rearrangements, and 15.4% of tumor samples did not have rearrangements of MYB or NFIB genes on FISH analysis." (PMID 39199639, 2024). "Results were available for twelve of fourteen patients; 83.3% (n = 10) of the tumors analyzed displayed MYB rearrangements at the 6q23.3 locus; 75% (n = 9) had NFIB rearrangements, and 17% (n = 2) of tumor samples did not have rearrangements of MYB or NFIB genes on FISH analysis." (PMID 39199639, 2024). "Interestingly, there appeared to be a greater proportion of BRN2/NFIB positive cells in metastatic tumours when compared with the primary samples (not quantified)." (PMID 28119061, 2017). "In this context, stable over-expression of NFIB limits the ability of these cells to upregulate vital components such as MITF, that may be required for the cells to adapt to changes in the local microenvironment in order to establish tumours." (PMID 28119061, 2017). "Interestingly, while the A2058− empty control cells were able to form tumours efficiently in 9/10 injection sites, A2058− NFIB cells failed to form tumours." (PMID 28119061, 2017). "Finally, interrogation of an independent data set from an alternative xenograft study also demonstrated elevated NFIB levels in highly metastatic tumours compared to the non-metastatic tumours (P < 0.05)." (PMID 28119061, 2017). "To investigate whether increased expression of NFIB improves survival in GBM, we next examined the effect of ectopic expression of NFIB on tumour growth using two widely used models of human GBM, U87 and U251 cell lines, which express low levels of NFIB compared to normal human brain." (PMID 27083054, 2016). "NFIB is likely to have a tumour suppressive role independent of MYB(L) in this cancer as truncation mutations specific to NFIB have also been found as have translocations involving other partners (e.g. NFIB-MAN1A1, NFIB-PTPRD, NFIB-NKAIN2, NFIB-XRCC4 and NFIB-AIG1)." (PMID 27083054, 2016). "While NFIB promotes tumor progression in murine SCLC, deletion of NFIB did not prevent metastasis, and its role in human disease remains undefined." (PMID 40419484, 2025). "However, to date, no previous studies have reported the roles of NFIB in the malignant development of KIRC and its mechanisms in the tumor growth and metastasis of KIRC." (PMID 33981484, 2021). "Using our previous microarray dataset, we determined that the expression of EZH2, RRM1 and FOXM1 was significantly increased in tumor compared with the non-tumor lung tissue and the expression of BTG2, NFIB and SELENBP1 was significantly decreased in the tumor compared to non-tumor." (PMID 30458017, 2018).